VWF (von Willebrand factor)
Diseases named in the same sentence as VWF in open-access papers (continued):
Sharing a sentence is not in itself a finding about the gene and the disease.
Von Willebrand disease (continued). "AvWS in ET arises from extreme platelet counts driving the adsorption and proteolysis of high‐molecular‐weight von Willebrand factor (VWF) multimers, producing a qualitative VWF defect akin to type 2A von Willebrand disease." (PMID 40625825, 2025). "von Willebrand disease (VWD) is characterized by absence or reduction of plasma von Willebrand factor (VWF) levels or reduced protein function." (PMID 40687385, 2025). "When there is a suspicion of von Willebrand disease (vWD), the standard laboratory screenings include tests for vWF antigen, activity of ristocetin cofactor, as well as the activity of Factor VIII coagulant." (PMID 40572775, 2025). "First described in 1926 by Erik von Willebrand, von Willebrand disease (vWD), the most prevalent inherited bleeding disorder, results from defects in von Willebrand factor (vWF), a multimeric glycoprotein involved in platelet adhesion and FVIII stabilization." (PMID 40868273, 2025). "Coagulation studies postoperatively revealed von Willebrand disease, with prolonged activated partial thromboplastin time and low VWF antigen (31.3), VWF:RiCoF, and factor VIII (47.6)." (PMID 40842737, 2025). "Coagulation factor deficiencies include hemophilia A (factor VIII deficiency), hemophilia B (factor IX deficiency), and von Willebrand disease (VWD), which affects von Willebrand factor (VWF) and impairs clot formation." (PMID 41140650, 2025). "Increased platelet counts can lead to VWF adsorption onto platelet surfaces, reducing the VWF plasma concentration and resulting in acquired von Willebrand disease." (PMID 40381108, 2025). "Von Willebrand Diseases (VWDs) comprise a spectrum of hemorrhagic disorders characterized by either a quantitative or qualitative defect in the Von Willebrand factor (VWF)." (PMID 39727438, 2024). "Patients with congenital von Willebrand’s disease (types 1 and 3) with reduced vWF: Ag levels also have reduced factor VIII activity." (PMID 38822325, 2024). "Inherited Von Willebrand disease (VWD) is characterized by either a net decrease in VWF monomers (as seen in Type 1 and Type 3) or abnormalities in HMW multimer formation (as seen in Type 2)." (PMID 39697971, 2024). "For patients with von Willebrand disease who are candidates for elective surgeries, von Willebrand factor concentrates or recombinant von Willebrand factor can be used." (PMID 38933711, 2024). "We found that patients with deficiencies of VWF (von Willebrand disease, VWD) had decreased CLU expression and ECs with low VWF expression also had low CLU expression." (PMID 38363768, 2024). "We identified clusterin (CLU) as a potential candidate regulator of VWF based on a single cell RNA sequencing (scRNA-seq) analysis in control endothelial cells (ECs) and von Willebrand disease (VWD) endothelial colony-forming-cells (ECFCs)." (PMID 38363768, 2024). "•von Willebrand factor Ristocetin co-factor activity to von Willebrand factor antigen level ratio (VWF:RCo/VWF:Ag) classifies von Willebrand disease." (PMID 38268521, 2024). "Quantitative, structural, or functional abnormalities of VWF lead to von Willebrand disease (VWD), a bleeding disorder with a prevalence of up to 1% in the general population, making it the most common genetic coagulation disorder." (PMID 33456057, 2023). "von Willebrand disease (VWD) is considered the most common bleeding disorder and arises from deficiency and/or defect in the adhesive plasma protein von Willebrand factor (VWF)." (PMID 37601016, 2023). "Concurrent measurements of vWF:Ag and electrophoretic analysis of vWF multimers in von Willebrand's disease patients suggest that this process is also dependent on the presence of high molecular weight vWF." (PMID 36937016, 2023). "Von Willebrand disease (VWD), the most common inherited bleeding disorder in humans, is caused by quantitative or qualitative defects in von Willebrand factor (VWF)." (PMID 33456057, 2023).
Von Willebrand disease (continued). "The diagnosis of Von Willebrand disease is based on measurements of Von Willebrand factor antigen, the level of Von Willebrand factor-dependent platelet adhesion, and the coagulant activity of factor VIII." (PMID 37685769, 2023). "Von Willebrand disease (VWD) is the most common congenital bleeding disorder, and is caused by a defect or deficiency of VWF in circulating blood." (PMID 38066509, 2023). "Individuals with dysfunctional VWF suffer from a bleeding disorder called von Willebrand disease (VWD)." (PMID 37240845, 2023). "For example, a 13-bp deletion in the promoter of the von Willebrand factor (VWF) gene in a patient with type 1 von Willebrand disease was assigned a PSV score of 63.2." (PMID 35484572, 2022). "Mutations in von Willebrand factor (VWF) and/or platelet glycoprotein Ib (GPIb), which alter their binding kinetics, induce hemostatic defects, such as von Willebrand disease." (PMID 35837553, 2022). "Quantitative or functional defects of VWF are known as von Willebrand disease (VWD), which is the most common inherited bleeding disorder in humans." (PMID 36430595, 2022). "Our experiments indicated that polyphosphate (polyP) increased the interaction of von Willebrand factor (VWF) with platelets in plasmas from severe hemophilia A and von Willebrand disease." (PMID 36430595, 2022). "The VWF test has been used primarily to diagnose von Willebrand disease (VWD), which is characterized by quantitative and/or qualitative defects in the VWF." (PMID 36684571, 2022). "Previously, we had reported a correlation between platelet polyP and plasma vWF by studying healthy individuals and patients with von Willebrand disease." (PMID 36364861, 2022). "This GOF phenotype resembles type 2B von Willebrand disease, in which large hyperadhesive VWF multimers bind to platelets, thus selectively being removed from plasma." (PMID 35411318, 2022). "Quantification of VWF:MM fractions, in addition to qualitative assessment of VWF:MM patterns, has the potential to aid in differential diagnosis of von Willebrand disease (VWD) subtypes." (PMID 35431650, 2022). "Recently, recombinant von Willebrand factor (rVWF) has become available for the treatment of bleedings in patients with inherited von Willebrand disease, but experience in patients with AVWS is limited." (PMID 35086107, 2022). "Since most patients with AS have acquired von Willebrand disease, desmopressin therapy has been applied successfully to increase von Willebrand factor multimers and reduce periprocedural bleeding." (PMID 35861798, 2022). "VWF is critically important both physiologically and pathologically, and dysfunction of VWF is responsible for several hemorrhagic disorders, including von Willebrand disease (VWD), a common hereditary disorder resulting from functional deficiencies in VWF." (PMID 35399372, 2022). "Elevated vWF levels are beneficial against von Willebrand’s disease in neonates as they help prevent cranial bleeding during childbirth." (PMID 35955419, 2022). "It is worth noting that moreover ADAMTS13 deficiency, also rare gain-of-function mutations in the A1 domain of VWF or in platelet GPIbα can result enhanced VWF-GPIbα interaction, even leading to thrombocytopenia (specific forms of von Willebrand disease)." (PMID 34943895, 2021). "A normal vWF antigen should also be documented to eliminate the possibility of some forms of von Willebrand disease." (PMID 34417909, 2021). "Von Willebrand disease is the most frequent congenital bleeding disorder in which there is either quantitative (type 1) or qualitative (type 2) defect in the von Willebrand factor (VWF)." (PMID 34722061, 2021). "This is particularly evident by the fact that dysfunction of VWF and loss of HMWM lead to the most common hereditary bleeding disorder, called von Willebrand disease (VWD)." (PMID 34572000, 2021).
Von Willebrand disease (continued). "Type Vicenza von Willebrand disease (VWD) features a von Willebrand factor (VWF) with a very short half‐life, and is classified as a form of type 1 VWD." (PMID 35844701, 2021). "A deficiency of VWF is associated with a bleeding disorder called von Willebrand disease (VWD), whereas an excess of VWF, in particular the HMW forms, is associated with thrombosis." (PMID 34564132, 2021). "All of these patients have had type 1 von Willebrand disease that was corrected by factor VIII/VWF complex or cryoprecipitate infusion." (PMID 34722061, 2021). "In a non-cancer setting, dDAVP is the treatment of choice in patients with von Willebrand disease (VWD; a genetic disorder caused by reduced or dysfunctional VWF) to stimulate the release of endogenous VWF into the plasma." (PMID 33571850, 2021). "Reduced or dysfunctional levels of VWF can lead to inherited von Willebrand disease (VWD), an inherited bleeding disorder." (PMID 34837956, 2021). "The study aimed to determine the levels of von Willebrand factor activity and activated partial thromboplastin time in women with menorrhagia and estimate the prevalence of von Willebrand disease in these women." (PMID 34394804, 2021). "Secondly, to evaluate the association between vWF activity and blood groups O verses blood groups A, B and AB in both cases and controls and finally to estimate the prevalence of von Willebrand disease based on vWF activity and aPTT in cases and controls." (PMID 34394804, 2021). "A defective VWF identifies von Willebrand disease (VWD), the most common inherited bleeding disorder." (PMID 35844701, 2021). "Despite the expected ameliorating effect of HD on platelet function, we did not observe any improvement post-HD in our patients who presented normal or increased vWF activity; thus ruling out the existence of von Willebrand disease." (PMID 34572522, 2021). "VWF had the highest number of HGMD heterozygous and novel variants, which is expected since Von Willebrand disease is the most common bleeding condition worldwide." (PMID 34272389, 2021). "There are three major types of von Willebrand disease (VWD), types 1 and 3 are caused by quantitative deficiency in von Willebrand factor (VWF) while a qualitative functional defect is the cause of type 2." (PMID 34235395, 2021). "The mechanism of impaired coagulation by colloids was reported by de Jonge and Levi through dilutional effect, molecular weight dependent reduction of vWF (acquired von Willebrand disease), factor VIII, and clot firmness." (PMID 32832150, 2020). "A study using a murine von Willebrand disease model found that SB transposon-mediated von Willebrand factor (VWF) gene delivery resulted in the long-term expression of supraphysiologic VWF levels." (PMID 32785089, 2020). "Von Willebrand disease (VWD) type 2B, for instance, is characterized by increased interactions between VWF and platelets, resulting from gain-of-function mutations (e.g. R1306W) in the VWF A1 domain." (PMID 30759116, 2019). "Another mechanism proposed is acquired von Willebrand disease from increased degradation of the von Willebrand factor (vWF) impaired platelet aggregation, leading to increased bleeding." (PMID 31938629, 2019). "We modified the routine ROTEM assay by adding a preincubation with ristocetin and commercially available plasma-derived von Willebrand factor to identify clinically relevant von Willebrand disease (VWD)." (PMID 30630422, 2019). "Dogs with AKI had decreased collagen‐activated platelet aggregation and appear to have a type II von Willebrand disease‐like phenotype as indicated by the high vWF:Ag:vWF:CBA." (PMID 31381195, 2019). "A structural or quantitative defect in the Von Willebrand’s Factor (VWF) leads to a bleeding disorder called Von Willebrand’s Disease (VWD)." (PMID 30607250, 2018).
Von Willebrand disease (continued). "About eighty percent of von Willebrand disease patients are diagnosed with a quantitative defect of von Willebrand factor (VWF) where fifty percent is due to an increased clearance of von Willebrand factor." (PMID 29992156, 2018). "Type 2B von Willebrand disease (VWD) is characterised by a greater affinity of von Willebrand factor (VWF) for platelet glycoprotein Ib (GPIb)." (PMID 28640903, 2017). "von Willebrand disease (VWD) is a hereditary bleeding disorder, caused by a deficiency in the levels and/or function of von Willebrand factor (VWF)." (PMID 27780267, 2016). "von Willebrand disease (VWD) is a genetically and clinically heterogeneous inherited hemorrhagic disorder caused by a deficiency or dysfunction of von Willebrand factor (VWF)." (PMID 27766062, 2016). "Von Willebrand disease (VWD) is a congenital bleeding disorder originating from quantitative or qualitative defects in von Willebrand factor (VWF), a multimeric glycoprotein essential for primary hemostasis." (PMID 27212476, 2016). "VWF quantitative reductions and/or abnormalities lead to von Willebrand disease (VWD), which is probably the most common inherited bleeding disorder." (PMID 27532107, 2016). "Von Willebrand Factor database or VWFdb is an online database that centers on von Willebrand disease." (PMID 26187044, 2015). "The von Willebrand disease (VWD) is a hereditary coagulation abnormality in humans caused by qualitative (type 2 VWD) or quantitative defects (type 1 and type 3 VWD) of the von Willebrand factor (VWF), a protein involved in hemostasis." (PMID 25635880, 2015). "The fundamental role of VWF in hemostasis is illustrated by the bleeding tendency of patients suffering from von Willebrand disease (VWD)." (PMID 25297919, 2015). "The vasopressin analogue desmopressin is used to increase plasma VWF levels in the treatment of von Willebrand disease." (PMID 26580395, 2015). "von Willebrand factor (vWF), the macromolecular plasma glycoprotein named for its contribution to the hereditary bleeding disorder known as von Willebrand disease (vWD), functions as a key regulator of primary hemostasis." (PMID 25886574, 2015). "Numerous approaches including genetically modified mouse models, various forms of von Willebrand disease, shear-induced thrombus formation, specific interactions with isolated A1 domain, etc. have been used for the characterization of vWF-induced signaling." (PMID 24705415, 2014). "This association, known as Heyde’s syndrome, is notably characterized by a coagulopathy, i.e., acquired von Willebrand disease, due to shear-stress mediated consumption of high molecular weight multimers of the von Willebrand factor." (PMID 24795637, 2014). "Von Willebrand disease (VWD) is an inherited hemorrhagic disorder promoted by either quantitative or qualitative defects of the von Willebrand factor (VWF)." (PMID 23970904, 2013). "Delivery in von Willebrand disease (VWD) represents a significant hemostatic challenge because of the variable pattern of changes observed during pregnancy of von Willebrand factor (VWF) and factor VIII (FVIII), the protein carried by VWF." (PMID 23936623, 2013). "Laboratory diagnosis of von Willebrand disease (VWD) requires determination of both von Willebrand factor (VWF) protein levels and activity." (PMID 23107512, 2013). "rFVIIa is an effective agent to treat refractory bleeding in von Willebrand disease patients and to treat or prevent bleeding in patients with alloantibodies or autoantibodies directed against von Willebrand factor." (PMID 23531278, 2013). "von Willebrand disease (VWD) is the most common inherited human bleeding disorder and is caused by quantitative or qualitative defects in von Willebrand factor (VWF)." (PMID 23049555, 2012).
Von Willebrand disease (continued). "In 4 out of 15 selected children with low ADAMTS-13 levels on admission, we found a remarkable reduction in the large and intermediate VWF multimers in the discharge blood samples, consistent with an acquired von Willebrand disease." (PMID 22563509, 2012). "The goal of the product development was to provide rVWF in an optimized ratio of VWF : RCo to FVIII : C to treat patients with severe von Willebrand disease (type 3)." (PMID 19763356, 2009). "While a deficiency of VWF is responsible for a hemorrhagic diathesis (von Willebrand disease, VWD), there are increasing evidences that elevated VWF levels represent an important thrombotic risk factor." (PMID 17894864, 2007). "Acquired von Willebrand syndrome (AVWS) is a rare bleeding disorder caused by defects in von Willebrand factor (VWF), an acquired condition that mimics the features of congenital von Willebrand disease and often develops secondary to underlying conditions, like a lymphoproliferative disorder (LPD)." (PMID 40895701, 2025). "During the studies with von Willebrand factor/Factor VIII-von Willebrand disease (SWIFTLY-VWD) trial, 4 children who received prophylaxis with the pdVWF/FVIII concentrate Voncento (CSL Behring) experienced a median of 23.5 nonsurgical BEs during 12 to 13 months of prophylaxis." (PMID 40224272, 2025). "Sixteen dogs had von Willebrand disease (one also had factor XI deficiency); three dogs had hemophilia A; and two dogs had normal concentration of von Willebrand factor and were not diagnosed with any hemostatic disorder." (PMID 41056368, 2025). "This variant has been observed in a patient who was in cis heterozygous for two VWF mutations and suffering from a noncanonical type 2B von Willebrand disease characterized by low VWF activity." (PMID 40671815, 2025). "Von Willebrand disease (vWD) is the most common inherited bleeding disorder and results from quantitative or qualitative defects of von Willebrand factor (vWF), a protein secreted by the vascular endothelium that mediates platelet adhesion and stabilizes factor VIII in the coagulation cascade." (PMID 41190197, 2025). "In addition, these results highlighted LSECs (the physiological source of factor VIII and von Willebrand factor) as an alternative and more physiologically relevant target than hepatocytes for hemophilia A57 or von Willebrand disease gene therapy." (PMID 39881029, 2025). "Type 1 von Willebrand disease (VWD1) is characterized by a partial quantitative deficiency of VWF, with plasma levels typically ranging from 5% to 50% of normal." (PMID 41337046, 2025). "Prolonged activated partial thromboplastin time (aPTT) and reduced activity of factor VIII (20.2%), von Willebrand factor (23.2%), and von Willebrand factor antigen (31.3%), as well as platelet hypofunction on aggregometry, led to a diagnosis of type 1 von Willebrand disease being made." (PMID 40799883, 2025). "Genetic defects in von Willebrand factor (VWF) can lead to von Willebrand disease (VWD)." (PMID 40529342, 2025). "Because of the ineffectiveness of treatment and persistently low levels of factor VIII and von Willebrand factor (vWF), the von Willebrand disease hypothesis was abandoned, prompting a new diagnosis for the bleeding disorder." (PMID 39105017, 2024). "Von Willebrand factor (VWF) is a large multimeric glycoprotein that plays an important role in hemostasis, illustrated by the bleeding tendency in von Willebrand disease, the most common inherited bleeding disorder caused by von Willebrand factor deficiency or dysfunction." (PMID 39494478, 2024). "The absence of VWF, as observed in type 3 von Willebrand disease, is associated with increased vascularization and severe clinical manifestations, such as gastrointestinal bleeding due to vascular malformations." (PMID 38825675, 2024). "This is the reason ISTH recommends failure to identify a causative mutation in the VWF gene does not rule out von Willebrand Disease." (PMID 35741733, 2022).